BRAF (B-Raf proto-oncogene, serine/threonine kinase)
Diseases named in the same sentence as BRAF in open-access papers (continued):
Sharing a sentence is not in itself a finding about the gene and the disease.
pyrexia (12 papers, 2015 to 2026). "Earlier ASCO results posited that pyrexia was associated with more durable responses under combination BRAF/MEK therapy." (PMID 41374434, 2025). "More severe reactions were rare: one BRAF-mutated patient experienced grade 3 pyrexia, which resolved after a 2-day treatment interruption, and one BRAF wild-type patient developed a transient grade 4 skin rash three days post-therapy completion." (PMID 39685478, 2024). "Subgroup analysis demonstrated that combination therapy was related to a more frequent incidence of pyrexia and gastrointestinal events and BRAF inhibition alone was at a high risk of dermatologic diseases." (PMID 31393083, 2019). "The dabrafenib–trametinib combination administered in two patients with BRAF p.V600E tumors entailed adverse events of grade 3–4, including skin rashes, pyrexia and a hydrothorax episode (in a patient with pelvic spindle-cell STS), necessitating dose reduction and therapy breaks in both cases." (PMID 41373618, 2025). "In contrast, in the published results of the randomized Phase II study (NCT02684058) of first-line dab + tram vs C+V in BRAF V600–mutant pLGG, the most common toxicity in the 73 patients on the dab + tram arm was pyrexia (68%), followed by headache (47%), and vomiting (34%)." (PMID 39839763, 2024). "Pyrexia was also at a higher rate in doublet therapy of BRAF and MEK inhibition." (PMID 31393083, 2019). "Similarly, pyrexia and dermatologic toxicities may correlate with outcomes under BRAF/MEK inhibition." (PMID 41374434, 2025). "Dabrafenib plus trametinib has demonstrated clinical efficacy in BRAF V600E-mutant NSCLC, although pyrexia frequently leads to treatment interruption." (PMID 42256653, 2026). "In parallel, ttAEs observed with BRAF and MEK inhibitors—including pyrexia, rash, arthralgia, photosensitivity, and laboratory abnormalities such as elevated liver enzymes—have also shown potential predictive implications." (PMID 41374434, 2025). "The etiology of pyrexia is not known for patients treated with BRAF inhibition and/or MEK inhibition therapies; however, this very common adverse event is often dose- and therapy-limiting." (PMID 31817473, 2019).
rectal adenocarcinoma (12 papers, 2014 to 2026). "Another distinct trait observed between colon and rectal adenocarcinomas is the predominance of mutations in v-Raf murine sarcoma viral oncogene homolog B1 (BRAF)." (PMID 39885557, 2025). "Currently, Ras-BRAF became a high-priority target also in advanced rectal patients given the prevalence of mutations in rectal adenocarcinoma." (PMID 30263096, 2018). "Overall mucinous rectal cancers are more likely to be MSI-H and to have KRAS, BRAF, and PIK3CA mutations when compared to rectal adenocarcinoma NOS." (PMID 32984045, 2020). "We report a 26-year-old male with rapidly progressive, BRAF V600E-mutant, microsatellite-stable (MSS) rectal adenocarcinoma, liver metastases, and PC presenting with bowel obstruction and inability for oral intake." (PMID 41920914, 2026). "The patient was a 53-year-old male with rectal adenocarcinoma (mismatch repair proficient, KRAS and BRAF wild-type) with pelvic and lung metastases." (PMID 32377194, 2020). "Due to metastatic rectal adenocarcinoma, RAS, BRAF V600E and PI3K molecular assay was performed and revealed that NRAS, BRAF V600E and PI3K was wild type but KRAS exons 2 had a mutation." (PMID 32375670, 2020).
Skin rash (12 papers, 2011 to 2025). A red eruption of the skin. "For example, skin rash and diarrhea associated with BRAF inhibitors in PCP patients can be managed through skin care and dietary adjustments." (PMID 40696244, 2025). "Establish a standardized prophylactic medication protocol, such as the preemptive use of topical corticosteroid creams to prevent and treat skin rash commonly associated with BRAF inhibitors." (PMID 41225509, 2025). "Overall, 32.97% of patients from the BRAF and MEK inhibitor treatment group had risk of rash compared with 38.40% in the control group, and 10.3% of patients in the BRAF and MEK treatment group developed alopecia, compared with 37.59% in the BRAF inhibitor control group." (PMID 39776585, 2024). "While our study has highlighted patient sex to be significantly associated with severe rash and its related outcomes, the underlying biological mechanism by which BRAF inhibitors cause rash, and the mechanism by which sex influences the risk of rash are not well understood." (PMID 32103736, 2020). "This early exanthema is usually treated by a dose reduction of the BRAF/MEK inhibitors in combination with topical steroids and only in rare, severe cases with systemic steroids." (PMID 34109122, 2021). "Skin rash is mostly seen in patients under treatment with BRAF inhibitors (64–71% with vemurafenib and up to 18% with dabrafenib)." (PMID 30693134, 2018). "TTP and OS to the ≥2nd line cetuximab-containing treatment according to KRAS, BRAF, PIK3CA mutations status, PTEN protein expression, AREG and EREG mRNA expression and grade of skin rash in the whole patient′ population." (PMID 21283802, 2011). "Additionally, isotretinoin was also recommended in the management of other types of skin rashes induced by oncologic medications, such as epidermal growth factor inhibitors, BRAF inhibitors, MEK inhibitors, and mTOR inhibitors." (PMID 39963639, 2025). "In contrast, exanthema is a common adverse event in patients treated with BRAF/MEK inhibitors." (PMID 34109122, 2021). "Skin rash has been reported in patients treated both with BRAF and MEK inhibitors." (PMID 30693134, 2018). "As far as TTP was concerned, the univariate analysis demonstrated significant associations with: i) KRAS mutations (p = 0.001); ii) BRAF mutations (p = 0.001); iii) AREG mRNA expression (p = 0.018); iv) EREG mRNA expression (p = 0.002) and v) the development of moderate severe skin rash (p<0.0001)." (PMID 21283802, 2011). "Multivariate analysis revealed KRAS (Hazard Ratio [HR] 4.3, p<0.0001), BRAF mutation (HR: 5.1, p<0.0001), EREG low expression (HR: 1.6, p = 0.021) and absence of severe/moderate skin rash (HR: 4.0, p<0.0001) as independent prognostic factors for decreased TTP." (PMID 21283802, 2011).
tubular adenoma (12 papers, 2013 to 2025). A usually polypoid neoplasm arising from the glandular epithelium. "The tubular adenoma with high-grade dysplasia was characterized by a BRAF p.V600E mutation and mismatch repair deficiency (loss of MLH1/PMS2)." (PMID 33712927, 2021). "On the other hand, BRAF mutation was identified in only 1 patient with tubular adenoma, emphasizing that there is likely a link between BRAF mutations and serrated lesions." (PMID 30774654, 2019). "In fact, demonstrating a rearrangement of MYB, MYBL1, PLAG1, HMGA2, NTRK3, and a BRAF mutation in the appropriate morphological context is diagnostic of adenoid cystic carcinoma, cutaneous mixed tumor, secretory carcinoma, syringocystadenoma papilliferum, and tubular adenoma." (PMID 35158743, 2022). "SAs involve BRAF mutations, CIMP, and MSI; tubular adenomas show chromosomal instability and global hypomethylation." (PMID 40731872, 2025). "In low grade intraepithelial neoplasia with mutant BRAF, 10 were tubulovillous adenomas, 8 were tubular adenomas, 26(26/52,50.0%) were serrated adenomas, and 4(4/7,57.1%) were villous adenomas." (PMID 26910894, 2016). "These expression profiles were associated with V600E BRAF mutation, a progressive accumulation of promoter methylation at specific CIMP loci and additional genes from the normal mucosa to tubular adenoma and RCT." (PMID 23425390, 2013). "Moreover, it is also presumed that the occurrence of the six polyps, including the serrated lesion, mesenchymal neoplasm, and tubular adenomas in the proximal colon, took part in both the BRAF and WNT signal pathways." (PMID 40091909, 2025). "A known pathogenic variant of BRAF (c.1799 T > A, p.Val600Glu) was detected in all SSLs analyzed (#2–1, #2–3, and #2–4), whereas we detected another two BRAF variants, not known to be pathogenic in the previous database, in tubular adenomas of patients." (PMID 36419139, 2022).
angiosarcoma (11 papers, 2015 to 2024). A malignant tumor arising from the endothelial cells of the blood vessels. "A recent deep sequencing study investigated mutations in the RAS/MAPK pathway comprehensively and found that 53% of angiosarcomas contained hotspot mutations in KRAS, HRAS, NRAS, BRAF, or MAPK1." (PMID 29872503, 2018).
B-cell lymphomas (11 papers, 2016 to 2025). "Overexpression of the oncogenic pseudogene BRAFP1 promotes the formation of human B-cell lymphomas through serving as a ceRNA of the parental gene BRAF." (PMID 35430805, 2022). "For instance, murine models engineered to overexpress the pseudogenes of the proto-oncogene BRAF develop an aggressive malignancy resembling human B cell lymphoma since, by functioning as ceRNAs, they elevate BRAF expression both in vitro and in vivo." (PMID 26812364, 2016). "Finally, there are transcriptional or genomic aberrations of human BRAF pseudogene (BRAFP1) frequently in multiple human cancers, including B cell lymphomas, suggesting the clinical significance of BRAF pseudogene." (PMID 30071685, 2018).
colitis (11 papers, 2021 to 2026). Inflammation of the colon. "A recent retrospective analysis comparing serrated polyps from colitis-affected and unaffected mucosa found BRAF mutations in 75% of SSL-like dysplasias from inflamed segments and in 100% of SSLs from non-inflamed mucosa." (PMID 41303078, 2025). "In conclusion, the risk of developing colitis should be accounted in patients treated with BRAF and MEK inhibitors, as it represents an uncommon adverse event with the potential to evolve into life-threating conditions, such as intestinal perforation." (PMID 34436699, 2022). "Our results revealed that 40% of patients recorded treatment-associated adverse events (TAE) of ≥CTCAE grade 1 during BRAF ± MEKi therapy including fever (11%), diarrhea (13%), or colitis (6%)." (PMID 34065877, 2021). "Conversely, BRAF V600E mutations are notably less frequent in colitis-associated CRC than in sCRC." (PMID 40102272, 2025). "KRAS mutations, which are less common in colitis-associated CRC, can influence the efficacy of anti-EGFR therapies, while BRAF V600E mutations, typically linked to poor prognosis, are uncommon in this context." (PMID 40102272, 2025). "The proportion of KRAS and BRAF mutations and CIMP-positive status in serrated polyps in colitis-affected segments tended to be higher in invasive cancer in colitis-affected segments in this study." (PMID 36827302, 2023). "KRAS and BRAF mutations and CIMP-positive status were observed in 13% (2/16), 0% (0/16), and 19% (3/16) of invasive cancers in colitis-affected segments." (PMID 36827302, 2023). "They described three cases of colitis (2 of them treated with BRAF and MEK inhibitors and 1 treated with MEK inhibitor alone), all of them presenting as watery diarrhea." (PMID 34436699, 2022). "Two patients died: one patient with metastatic BRAF-mutant disease treated with second-line ipilimumab/nivolumab who developed colitis complicated by sepsis, and one patient treated with first-line ipilimumab/nivolumab who developed immune-related encephalitis." (PMID 36290906, 2022). "In particular, BRAF mutations and CpG island methylator phenotype (CIMP), together with loss of MLH1 in dysplastic SSLs, have been described in IBD cohorts, suggesting that a serrated route to CRC may operate alongside the conventional adenoma–carcinoma sequence, especially in long-standing colitis." (PMID 41303078, 2025). "Severe gastrointestinal toxicities are uncommon with BRAF and MEK inhibitors, although cases of colitis and intestinal perforation have already been reported in literature." (PMID 34436699, 2022).
colorectal adenoma (11 papers, 2006 to 2016). An adenoma that arises from the colon or rectum. "There were only 7.1% (27/378) BRAF V600E mutations present in other types of colorectal adenomas (tubular, tubulovillous and villous adenomas)." (PMID 26910894, 2016). "A previous analysis of 113 unselected sporadic colorectal adenomas detected BRAF mutations at a frequency of only 2.8%." (PMID 20233436, 2010). "Somatic mutation frequencies and spectra at APC, K-ras and BRAF were, however, similar to those in sporadic colorectal adenomas." (PMID 17505512, 2007). "BRAF mutation frequencies of 0%14 and 3%31 have been reported in other series of colorectal adenomas." (PMID 16879389, 2006). "Although BRAF mutations occur early in colorectal carcinogenesis and have been observed in colorectal adenomas, tumor progression needs additional acquired DNA microsatellite instability caused by hypermethylation of MLH1 in the setting of the CpG island methylator phenotype (CIMP)." (PMID 25005754, 2014). "Similarly, BRAF mutations have been found in colorectal adenomas suggesting an early event in tumorgenesis." (PMID 24066160, 2013). "Accordingly, most of colorectal adenomas analyzed herein exhibited KRAS (G12D, G13D, Q61H) or BRAF (V600E) activating mutations, in combination with APC inactivating mutations (exon 15)." (PMID 27582544, 2016). "Though coexistence of mutations occurring in BRAF or KRAS has been assumed to be mutually elusive, such phenomena were recently observed in colorectal adenoma/cancer and ovarian malignancies." (PMID 24139521, 2013). "In the current study, we examined K-ras/BRAF mutations and methylation status of RASSF1 and RASSF2 in colorectal adenomas in relation to clinicopathological features." (PMID 17923875, 2007). "In this study, therefore, we investigated K-ras and BRAF mutations and the methylation status of RASSF1 and RASSF2 in colorectal adenoma samples." (PMID 17923875, 2007). "We analysed K-ras/BRAF mutations and the methylation status of RASSF1 and RASSF2 promoter regions in 120 colorectal adenomas with respect to their clinicopathological features." (PMID 17923875, 2007). "Furthermore, KRAS and BRAF are likely involved in the malignant transformation of colorectal adenomas as driver genes." (PMID 26910894, 2016). "Finally, we show that E2F4 is overexpressed, phosphorylated and localized in the nucleus of epithelial cells from colorectal adenomas exhibiting APC and KRAS or BRAF mutations." (PMID 23919615, 2013). "Finally, E2F4 was found to be overexpressed, phosphorylated and nuclear localized in epithelial cells from human colorectal adenomas exhibiting mutations in APC and KRAS or BRAF genes, known to deregulate GSK3/β-catenin and MEK/ERK signaling, respectively." (PMID 23919615, 2013).
heart failure (11 papers, 2019 to 2025). Inability of the heart to pump blood at an adequate rate to meet tissue metabolic requirements. "Regarding cardiac failure and left ventricular failure, a meta-analysis found that treatment with BRAF/MEKi (including D + T, V + C, and E + B) was associated with a decrease in the left ventricular ejection fraction (LVEF) compared to BRAFi monotherapy." (PMID 40507236, 2025). "Combination therapy was associated with a higher risk of heart failure (OR: 1.62; 95% CI: 1.14-2.30) in comparison with BRAF inhibitor monotherapy." (PMID 35492830, 2022). "BRAF is a key signalling intermediate that causes cancer and is up-regulated in heart failure, but its role in physiological and pathological cardiac hypertrophy remains to be established." (PMID 36331065, 2022). "On balance, it seems appropriate to consider that the increase in BRAF expression in heart failure is potentially an important facet of the disease." (PMID 35147166, 2022). "BRAF was up-regulated in heart samples from patients with heart failure compared with normal controls." (PMID 35147166, 2022). "This study showed that BRAF is up-regulated in human heart failure and activation of BRAF in cardiomyocytes promotes cardiomyocyte hypertrophy." (PMID 35147166, 2022). "Up-regulation of BRAF in separate cohorts of heart failure patients, with selective up-regulation of BRAF and down-regulation of RAF1 and ARAF isoforms in patients with dilated cardiomyopathy, suggests that the changes are a key feature of a failing heart." (PMID 35147166, 2022). "BRAF expression is up-regulated in dilated cardiomyopathy and heart failure, suggesting it plays a role in human heart diseases." (PMID 36331065, 2022). "For instance, recently, it was shown that BRAF was elevated in humans with heart failure." (PMID 38892401, 2024). "Here, we show that BRAF expression is up-regulated in human heart failure." (PMID 35147166, 2022). "In addition, the role of BRAF and its activation in overt heart failure remains to be established." (PMID 36651286, 2023). "Our aims were to determine if BRAF is relevant for human heart failure, whether BRAF promotes cardiomyocyte hypertrophy, and if Type 1 RAF inhibitors developed for cancer (that paradoxically activate ERK1/2 at low concentrations: the ‘RAF paradox') may have the same effect." (PMID 35147166, 2022). "BRAF and MEK inhibition are connected to left ventricular systolic dysfunction and heart failure, with a higher incidence when used in combination therapy." (PMID 39583362, 2024). "Even if BRAF is not a driving force in the development of human heart failure, an increase in BRAF expression (and potentially, BRAF activation) may influence the failing phenotype." (PMID 35147166, 2022). "BRAF and RAF1 (but not ARAF) mRNA and protein were significantly up-regulated in samples from a cohort of 12 patients with heart failure of mixed non-ischaemic aetiology compared with normal controls." (PMID 35147166, 2022).
medulloblastoma (11 papers, 2015 to 2026). A malignant, invasive embryonal neoplasm arising from the cerebellum. "These authors noted that during the study period, there were suggestions for molecular testing, including BRAF fusion/mutation, medulloblastoma subgrouping, and genetic testing." (PMID 38764578, 2024). "Among the 52,519 tumors with BRAF mutations currently cataloged in the COSMIC database [version 85 release], only one other tumor (medulloblastoma) with a small in-frame insertion at this site is present." (PMID 29880043, 2018). "The remaining unresolved cases (10 cases with non-BRAF/non RELA/ZFTA fusions and 16 non-WNT/non-SHH medulloblastoma) can then be subjected to NanoString, NGS, or other advanced molecular testing methods." (PMID 38764578, 2024).
melanocytic nevus (11 papers, 2011 to 2026). A neoplasm composed of melanocytes that usually appears as a dark spot on the skin. "In this context, it is also interesting to note that melanocytic naevi with mutations in the NRAS signalling pathway (NRAS or BRAF mutations) require additional driver mutations to avoid senescence, e.g., in the CDKN2A locus." (PMID 33138083, 2020). "One possible explanation is that these cells with BRAF mutations undergo senescence, as has been demonstrated in melanocytic nevus." (PMID 21224857, 2011). "Based on this finding, it is presumed that many PEMs can harbor BRAF V600E mutations and in these instances, they arise due to a genetic alteration that leads to PRKAR1A inactivation in a conventional or common acquired melanocytic nevus which typically has BRAF V600E mutations." (PMID 34943205, 2021). "We detected the BRAF p.V600E mutation in 78.6 % of dermal and/or junctional melanocytic naevi." (PMID 26141748, 2015).